RECQL4 (RecQ like helicase 4)
Diseases named in the same sentence as RECQL4 in open-access papers (continued):
Sharing a sentence is not in itself a finding about the gene and the disease.
tumor (62 papers, 2008 to 2026). "Recent studies have indicated that the overexpression of RECQL4 is common across various tumor types and is significantly associated with poorer clinical outcomes." (PMID 41513625, 2026). "High tumour purity and limited signatures of tumour immunogenicity associated with response to anti‐PD‐1 correlated with high RECQL4 activity." (PMID 39812592, 2025). "Lastly, bioinformatic analysis reveals that high levels of RECQL4 are correlated with increased tumor mutation burden." (PMID 36126066, 2022). "Using bioinformatic/meta-analysis, we show that increased RECQL4 levels is associated with increased tumor burden, mutations, and therapeutic response." (PMID 36126066, 2022). "As elevated Hrq1 protein levels in yeast result in increased mutations, we postulated that increased human RECQL4 expression correlates with increased tumor mutation burden." (PMID 36126066, 2022). "Overexpression of RECQL4 due to gene amplification has been reported to be associated with tumor progression of many human malignant cancers." (PMID 33628589, 2021). "In primary tumors, high RECQL4 expression was positively associated with tumor differentiation, depth of invasion, and lymph node metastasis." (PMID 33628589, 2021). "RECQL4 (a member of the RECQ helicase family) upregulation has been reported to be associated with tumor progression in several malignancies." (PMID 33628589, 2021). "To understand if loss of Recql4 altered the biology of the OS that arose, we analysed a range of tumor characteristics." (PMID 25859855, 2015). "In this study, we found that RECQL4 expression was aberrantly elevated in both clinical LUAD tissues and tumor cell lines, and higher levels of RECQL4 expression were associated with poor prognosis and worse clinicopathological characteristics in LUAD patients." (PMID 41513625, 2026). "Our findings show that RECQL4 expression has divergent patterns across tumor types and that targeting RECQL4 may dampen tumor survival and enhance susceptibility to ATR inhibitor therapy in CNS tumors." (PMID 41317405, 2025). "Clarification of the structure and functions of RECQL4, and discovering novel mutations may support the rationale for personalization of tumor therapy based on the genetic testing of the RECQL4 gene." (PMID 41419455, 2025). "Additionally, RECQL4 overexpression was associated with worse survival outcomes, including poor tumor differentiation, lymph node invasion, and metastatic disease." (PMID 35782872, 2022). "Increased oxidative stress and DNA damage caused by RECQL4 depletion could drive cellular senescence and thereby inhibit tumor progression." (PMID 33628589, 2021). "This CIN phenomenon has the potential to drive tumour growth, worsen patient prognosis, promote resistance to anticancer therapies, and could be both, a causative factor or a consequence of the presence of RECQL4 high amplification." (PMID 39812592, 2025). "Furthermore, we detected a greater prevalence of RECQL4 high amplification in metastatic lesions compared to primary tumours, but also a predisposition for RECQL4 high amplification (57%) in metastases of multiple tumour entities compared to the diploid status (39%) (p = 7.11e‐24)." (PMID 39812592, 2025). "Thus, our working hypothesis is that aneuploidy and tumor predisposition can only arise in cells retaining the Sld2-homology regions of RECQL4 where basal cell proliferation is intact but genomic stability is compromised." (PMID 25859855, 2015). "Thus, RecQL4 may serve as a double-edged sword whose loss or gain of expression is associated with human tumor progression." (PMID 23894508, 2013).
tumor (continued). "To further investigate the impact of RECQL4 on proliferation ability in vivo, we conducted xenograft subcutaneous tumor formation experiments utilizing BALB/c-nude mice." (PMID 41513625, 2026). "According to the IHC analysis, the RECQL4 expression was significantly increased in LUAD tissues compared to the corresponding tumor-adjacent tissues." (PMID 41513625, 2026). "Subsequently, we conducted IHC on a tissue microarray that included 84 pairs of LUAD tissues and corresponding tumor-adjacent tissues in order to assess the level of RECQL4 protein expression." (PMID 41513625, 2026). "Subsequently, we used H&E staining to assess tumor morphology, while IHC analysis was utilized to evaluate the expression levels of RECQL4 and Ki-67." (PMID 41513625, 2026). "Samples exhibiting high RECQL4 expression displayed significantly lower immune scores (p = 6.6e‐08) and higher tumour purity (p = 2.34e‐05)." (PMID 39812592, 2025). "Confirming RECQL4’s independence from MKI67 as a prognostic factor would imply that RECQL4’s influence on patient prognosis extends beyond tumour proliferation rate." (PMID 39812592, 2025). "To delineate the genes and pathways that are differentially regulated in tumours with RECQL4 CNA, we grouped samples of the TCGA SKCM cohort according to the RECQL4 CNA status (diploid and high‐amplified) and performed gene expression analyses." (PMID 39812592, 2025). "Functionally, RECQL4 knockdown sensitizes tumor cells to ATR inhibition, suggesting a potential therapeutic vulnerability in the clinical setting and possibly, a diagnostic role of RECQL4 IHC for treatment selection." (PMID 41317405, 2025). "High RECQL4 transcript per million (TPM) levels in 31 tumor types correlated significantly with shorter patient OS (HR of 1.8)." (PMID 40196015, 2025). "We found alterations in the secretion profile of immune regulatory factors and immune‐related pathways robustly suppressed in tumours with high RECQL4 levels, underscoring its crucial role in fostering immune evasion." (PMID 39812592, 2025). "They demonstrated that tumor-derived RECQL4 inhibits the activation of the DC cGAS-STING pathway, thereby interfering with anti-tumor immune reconstitution following radiotherapy and ultimately reducing HCC sensitivity to treatment." (PMID 41438738, 2025). "Anwar et al20 identified 17 genes in 90% of the Ghanian tumours that had recurrent CNV’s with the most frequent gains observed in RECQL4 (8q24.3) and SDHC (1q23.3) genes in 50% and 60% of cases, respectively." (PMID 40813389, 2025). "RECQL4, UTP6, CCNT1, and NSUN5 were enriched in the regulation process of cyclin dependent protein kinase activity, Cyclin D1 is one of the effectors of tumor gene Neu and Ras causing malignant transformation of cells in breast cancer." (PMID 39095659, 2024). "It was confirmed that RECQL4 was upregulated in tumor tissues compared to that in adjacent non‐tumor controls (P<0.0001)." (PMID 38381090, 2024). "The involvement of the cGAS‐STING pathway in the RECQL4‐mediated tumor‐promoting immune blockade was tested in vivo." (PMID 38381090, 2024). "In summary, our data provided the first evidence of a relationship between tumor‐derived RECQL4 and cGAS/STING activation in radiation‐triggered DCs in HCC." (PMID 38381090, 2024). "This is also possible because within the BLM gene, resides the RecQ homologs, in particular, the RecQL4 helicase acts as a tumor suppressor." (PMID 37796556, 2023). "The RECQL4 harboring chromosome region (8q24.3) became amplified, and the level of amplification corresponded with tumor aggressiveness." (PMID 35782872, 2022). "For SigIQvar8, two genes (SNHG10 and RECQL4) are risk factors for ACC progression after adjusting for age at diagnosis and tumor stage." (PMID 35681785, 2022). "All three co-amplified genes were significantly overexpressed in tumor samples (left) and RECQL4 possessed significantly higher expression levels in the MIP subtype (right) in the TCGA-LUAD cohort." (PMID 35992814, 2022).
tumor (continued). "In comparison to the normal tissues, a remarkably upregulated RECQL4 expression was observed in the tumor tissues." (PMID 34486474, 2021). "Tumour spheres from control (siCTRL) or RECQL4-depleted cells (siRECQL4) were visualized with light microscopy after 7 days of culture, and spheres of ≥ 100 μm in diameter were counted." (PMID 33050631, 2020). "We found numerous specimens with positive RECQL4 staining more abundant in tumours versus normal brain tissues." (PMID 33050631, 2020). "RECQL4 is involved in many intracellular regulatory pathways and can act either as an oncogene or a tumor suppressor gene." (PMID 32508881, 2020). "For the tumor suppressors, there are 3 up-regulated genes (mutations: POLE; CNAs: DNMT3B, RECQL4) and 2 down-regulated genes (CNAs: SDHA; fusions: ZFHX3)." (PMID 32934781, 2020). "These limitations confound the understanding of the in vivo role of Recql4 in both normal development and tumor formation." (PMID 25859855, 2015). "RECQL4 expression is significantly different in tumor (0.067±0.113, median = 0.014, p = 0.033) and in cell lines (0.396±0.199, median = 0.37, p = 0.0001) than normal (0.059±0.154, median = 0)." (PMID 23874974, 2013). "RECQL4 expression is limited up to an average of 1.12(±1.9) fold change in tumor but in cell lines it goes up to 6.7(±3.3) folds in cell lines." (PMID 23874974, 2013). "Compared to mice injected with parental and control shRNA transduced cells, the tumor size was dramatically reduced in mice injected with RecQL4 suppressed stable cell lines." (PMID 23894508, 2013). "Conversely, overexpression of Recql4 was reported in human OS tumours with chromosomal abberations and instabilities in the 8q24 locus, which also contains c-Myc." (PMID 23036272, 2012). "In addition, RECQL4 plays a dual role in DNA replication and repair mechanisms in normal and tumour cells." (PMID 39812592, 2025). "Next, we asked which immune cells are targeted by RECQL4 CNA for its presentation in tumour tissue." (PMID 39812592, 2025). "In light of these findings, we postulated that recruitment of cells from the tumour microenvironment, including cells of the immune compartment, might be constrained under conditions of elevated RECQL4 copy number." (PMID 39812592, 2025). "Mechanistically, our gain and loss of function analyses have unveiled a notable downregulation of major MHC‐II molecules following RECQL4 overexpression, concomitant with alterations in the secretion of immune‐regulatory factors that foster an immunosuppressive tumour microenvironment." (PMID 39812592, 2025). "Thus, we propose that the increased FGA in these tumours induces RECQL4 high amplification, leading to enhanced RECQL4 expression for proficient DNA damage repair within the tumours." (PMID 39812592, 2025). "Interestingly, our data clearly show that RECQL4 high amplification and expression correlated with downregulation of immune‐related pathways and reduced intra‐tumoural recruitment of immune cells, including T cells." (PMID 39812592, 2025). "Additionally, overexpression of RECQL4 also suppressed the mRNA and protein expression of interferon‐γ in RT‐treated tumor tissue." (PMID 38381090, 2024). "Interestingly, the same fractionated dose also induced secondary tumor growth in RECQL4‐overexpression mice as compared to that in the control group." (PMID 38381090, 2024). "Therefore, RECQL4 is deeply involved in maintaining genome stability and is classified as a tumor suppressor gene." (PMID 36975488, 2023). "We detected the germline variants of RECQL4, CNTNAP2, and PRDM2, which are tumor suppressor genes." (PMID 36975488, 2023). "TRIM58 acts as a tumor suppressor in CRC through the promotion of RECQL4 ubiquitination and inhibition of the AKT signaling pathway and may be investigated for the successful treatment of CRC." (PMID 37516854, 2023). "The findings showed higher RECQL4 expression in most tumor tissues." (PMID 37626815, 2023).
tumor (continued). "Furthermore, miR-10a-5p, a tumor suppressor, negatively regulates RECQL4 expression, thus suggesting its role in RECQL4 overexpression and, subsequently, oncogenic effect." (PMID 35782872, 2022). "Additionally, high levels of RECQL4, MXD3, and PRR7 mRNA expression are associated with advanced tumor stages." (PMID 35681785, 2022). "In addition, we established a subcutaneous xenograft model to determine the role of RECQL4 in tumor growth in vivo." (PMID 33628589, 2021). "Remarkably, FC osteoblasts could maintain a certain clonal growth ability in soft agar, implying a potential tumor suppressor role of RECQL4 at the tumor imitation stage." (PMID 34965247, 2021). "According to the CPTAC data, the protein expression of PKMYT1, ETF1, ECT2, BUB1B, and RECQL4 in tumor tissues was significantly increased, while the expression of TFRC was significantly reduced, and the expression of COCH and TUBB2B did not change significantly (PITX1 and CDC6 were not included)." (PMID 33869220, 2021). "Taken together, these results suggest that RECQL4 is a pleiotropic gene and that lifespan and perinatal mortality are not correlated in such a pleiotropic tumor suppressor gene-deficient C57BL/6 mice." (PMID 34117297, 2021). "Depletion of RECQL4 also inhibited growth of tumor xenografts in vivo." (PMID 33628589, 2021). "Indeed, both the primary tumor and corresponding PDX harbored a truncating mutation in RECQL4 (F987*), a gene which has a role in DNA repair by homologous recombination." (PMID 32332851, 2020). "Furthermore, RECQL4 mRNA expression was found to be significantly overexpressed across different human tumor types." (PMID 33014878, 2020). "Finally, we found 3 pathogenic/likely-pathogenic mutations in ERCC3, RECQL4 and TSC2 genes, encoding transcription factors and tumor suppressors." (PMID 28423363, 2017). "Among them, INHBA and RECQL4 were frequently overexpressed and amplified in various tumor types." (PMID 28377632, 2017). "In addition, we performed IHC analysis to evaluate the expression levels of NF-κB (p65) in xenograft subcutaneous tumor, and the results showed that the expression of NF-κB (p65) was significantly decreased in the sh-RECQL4 group, while the opposite result was observed in the oe-RECQL4 group." (PMID 41513625, 2026). "Thus, RECQL4 high amplification may affect patient prognosis due to the limited number of immune cells and modulation of immune‐related pathways in these tumours." (PMID 39812592, 2025). "In our analysis, RECQL4 expression showed divergent patterns across tumor types, being upregulated in HGG but reduced in MPNST, particularly NF1-associated cases, suggesting that its biological role and potential as a therapeutic target may be context-dependent." (PMID 41317405, 2025). "Since tumour cells display enhanced proliferation relative to most normal cells, with the exception of progenitor and stem cells, targeting the replication machinery through RECQL4 seem to be a promising strategy with limited consequences for non‐cancerous cells." (PMID 39812592, 2025). "Moreover, western blotting of the tumor showed that TRIM58 inhibited the expression of RECQL4." (PMID 37516854, 2023). "It is possible that the increased mutations observed with RECQL4 over-expression elicits a tumor immune response that is not observed in cultured cells or perhaps the small sample size or cohort analyzed may be distinct." (PMID 36126066, 2022). "Moreover, RECQL4 overexpression was negatively regulated by the tumor suppressor miR-10a-5p." (PMID 33014878, 2020). "Therefore, together with the present data, we conclude that the RECQL4 is not an OS tumor suppressor when the mutation results in a null allele." (PMID 25859855, 2015).
tumor (continued). "Indeed, we have not seen tumor formation in Recql4 deficient animals or aged Recql4+/- animals of any type." (PMID 25859855, 2015). "RECQL4 is a member of a family of DNA helicases including Bloom (BLM) and Werner (WRN) helicases, All three members are associated with familial cancer predisposition syndromes with high frequencies of mesenchymal derived tumours, with RTS in particular developing OS at approximately 30% frequency." (PMID 23036272, 2012). "RecQ-like helicase 4 (RECQL4), a member of the DNA helicase family, plays a crucial role in DNA replication, DNA damage repair, and tumor progression." (PMID 41513625, 2026). "The combined effect of RECQL4‐induced changes in soluble factor secretion and MHC‐II downregulation likely facilitates tumour immune evasion, potentially elucidating the attenuated response to ICI therapy in patients exhibiting elevated RECQL4 expression." (PMID 39812592, 2025). "The results demonstrated that EEF2, G3BP1, G3BP2, PRPF8, RECQL4, STOML2, and UBB exhibited significantly higher expression levels in the majority of tumor tissues, whereas METTL3 and NR2C2 showed a widespread downregulation trend." (PMID 41341921, 2025). "The analysis results showed that the expression levels of G6PD, KIF20A, NDRG1, RECQL4, and MCM4 were significantly higher in HCC tumor tissues than in normal tissues, while ADH1C was significantly downregulated in HCC tumor tissues." (PMID 41169384, 2025). "The cGAS‐STING pathway is a key regulator of tumor CD8+ T cell infiltration and is regulated by RECQL4." (PMID 38381090, 2024). "Using various genetically engineered mouse models, we found that tumor‐derived RECQL4 inhibited cGAS‐STING pathway activation in dendritic cells and anti‐tumor immune reorganization after RT, thereby reducing the sensitivity to HCC treatment." (PMID 38381090, 2024). "On the other hand, RECQL4 overexpression reduces the recruitment of DCs and CD8+ T cells, reducing the “soil” on which cGAS‐STING and IFN‐I are produced, leading to tumor immune evasion." (PMID 38381090, 2024). "RECQL4 repairs dsDNA released by tumor cells during RT, suppresses cGAS‐STING signaling in DCs, and prevents radiation‐induced tumor immune awakening." (PMID 38381090, 2024). "Mechanistically, the inhibitory effect of RECQL4 on radiotherapy is due to the reduced recruitment of dendritic cells and CD8+ T cells in the tumor microenvironment (TME)." (PMID 38381090, 2024). "We showed that RECQL4 was remarkably overexpressed in ESCC tissues, especially in metastases, and was positively correlated with poor tumor differentiation, lymph node metastasis, and advanced stage." (PMID 33628589, 2021). "RECQL4 protein expression was first examined in 197 surgical specimens taken from ESCC patients and the paired adjacent non-tumor tissues using an IHC assay." (PMID 33628589, 2021). "Frequent over expression of MCM10, which partners with RECQL4 and binds to MCM2-7 complex activating its helicase activity, indicates that MCM10 is critical in the tumor progression." (PMID 23874974, 2013). "RT–PCR and immunohistochemistry on independent cases validated prognostic significance for several genes including RECQL4, FRRS1, CFH and MET – whose combined expression carried greater prognostic value than tumour grade – and cmet and TRKB proteins." (PMID 18382428, 2008). "Furthermore, considering the physical proximity of the MYC oncogene to the RECQL4 gene locus, coupled with MYC’s established impact on tumour progression and immune evasion, we included MYC expression as a variable in our multivariate analyses." (PMID 39812592, 2025). "Therefore, the prognostic significance of LIHC was significantly influenced by factors such as pathological stage, tumor status, and the expression levels of RECQL, WRN, RECQL4, and RECQL5." (PMID 37626815, 2023).